MYC (MYC proto-oncogene, bHLH transcription factor)
Diseases named in the same sentence as MYC in open-access papers (continued):
Sharing a sentence is not in itself a finding about the gene and the disease.
tumor (continued). "Therefore, the higher expression of E2F, MYC, and miR-17-5p in invasive and proliferative tumours (grade 3) than in grade 1 (non-invasive tumours) confirms that both invasiveness and proliferation must be taken into account in PitNET classification." (PMID 32316225, 2020). "Ninety-six percent of the tumor cells were found to have MYC/IgH gene fusion as determined by FISH." (PMID 32035483, 2020). "In summary, these results contribute to a better understanding of the tumour suppressor effects of metformin, by showing that the drug decreases the expression of several important oncoproteins, including c-MYC, VEGF and β-catenin, and likely does so via a pathway involving miR modulation." (PMID 33081077, 2020). "The fact that basal-TNBC and CL-TNBC tumours had similar expression levels of MYC yet very different expression levels of CD36, LPL, PDK4 and FABP4 suggested that there are likely other factors, besides MYC, that direct activation of FAO and lipid metabolism in CL-TNBC." (PMID 31942031, 2020). "(E) DNA-FISH validation of somatic mosaicism of the SKIL and MYC amplicons in tumor P6." (PMID 32401198, 2020). "MYC is a potent oncogene that drives tumor initiation and maintenance." (PMID 33127915, 2020). "Because of the ability to recruit stromal and infiltrating immune cells to promote invasive growth, MYC could also be called “the master regulator of tumor microenvironment”." (PMID 33081056, 2020). "In addition, DFMO depletes tumours of polyamines and inhibits the growth of MYC‐deregulated tumours in animals." (PMID 33030764, 2020). "Interestingly, human DIPG and H3.3K27M-driven mouse tumours both develop secondary RAS/MAPK/PI3K pathway and MYC mutations." (PMID 33277484, 2020). "Finally, the tumor suppressor activity of P21 can be promoted by interaction with tumor-related factors like MYC, proliferating cell nuclear antigen (PCNA), and signal transducer and activator of transcription (STAT3)." (PMID 31998417, 2020). "Moreover, MYC is able to promote tumor growth and aggressiveness by recruiting stromal and tumor-infiltrating cells." (PMID 33081056, 2020). "However, nuclear expression of c-MYC was detected in 85% (17/20) of clinical specimens and was frequent (≥30% of tumor cells) in 15% of them (3/20)." (PMID 32429395, 2020). "Thus, MKK3 can play a dual role in cancer: one as a lost tumor suppressor acting through the p38-pathway, and another as an oncogene through upregulation of different oncogenic programs, such as the MYC transcription." (PMID 32873298, 2020). "Some of these genes, which interfere with tumor cell growth/differentiation/migration/invasion (such as MYC, MET, PROM1, and PTK2), induce hypoxia (such as ARNT2, HIF3A, TGB2, MMP2, and POSTN) and genes regulating transcription via acetylation were downregulated upon pembrolizumab treatment." (PMID 32616706, 2020). "Although it is well known that MYC is able to induce genomic instability, a fundamentally important feature of cancer cells, tumor microenvironment can also induce important genetic alterations in the surrounding cells, demonstrating that MYC and TME are allies in cancer progression." (PMID 33081056, 2020). "This specific stromal reprogramming could be fully reversed by deactivating MYC, which also leads to tumour regression." (PMID 31819196, 2020). "Overall, our data indicate that elevated levels of both active c-MYC and FASN gene are predictors of poor prognosis in this aggressive tumor, and suggest the functional interplay between c-MYC and FASN also in human HCC, as demonstrated in in vitro and in vivo models." (PMID 33187130, 2020). "Furthermore, gene sets for MYC targets and Wnt/β catenin signaling that support tumor cell growth and inhibit differentiation were significantly downregulated." (PMID 32366905, 2020).
tumor (continued). "This high concordance rate suggests that CTC may show a complementary role for tumor tissues in the assessment of the c-MYC status in clinical practice, especially for recurrent or metastatic cases." (PMID 31454863, 2020). "The MYC oncoprotein has been verified to stimulate tumor cell growth and proliferation through the amplification of gene transcription; therefore, inhibiting MYC function might be an attractive therapeutic option." (PMID 32128448, 2020). "However, similarly to E2F1, we found a positive relationship between MYC expression and tumour invasiveness, although only in the ST subtype." (PMID 32316225, 2020). "Together, these results suggest that differences in MYC levels between tumour and stromal cells or within a tumour could aid tumour expansion by inducing super-competition." (PMID 31102668, 2020). "Additionally, ectopic expression of miR-33b inhibits tumorigenesis in vitro and in vivo by directly targeting MYC, indicating that this miRNA plays a tumor suppressor role in GC." (PMID 32150871, 2020). "Moreover, the upregulated c-MYC cooperates with mutant ras through programming inflammation and suppressing the tumour immunity, and c-MYC acts by cell selection promoting proliferation versus apoptosis depending on the supply of growth factors." (PMID 33228223, 2020). "Activation of the oncogene c-MYC and tumor microenvironment remodeling account for FL progression." (PMID 33168041, 2020). "We found that 15 UCB patients harbored CNV in all 3 exons of MYC gene in the tumor tissue." (PMID 33298978, 2020). "Additionally, the Western blotting data showed that the amounts of p‐ERK1 (Thr202/Tyr204), p‐c‐MYC (Ser62), c‐MYC in the PRKD3‐knockout xenograft tumours were lower than these in the parental xenograft tumours." (PMID 31944568, 2020). "Although MYC is an important target in tumor cells, MYC has not been therapeutically targeted in tumor-associated macrophages in vivo." (PMID 32685002, 2020). "In ALCL tumor-derived cell lines, MYC overexpression increased PD-L1 expression." (PMID 32549409, 2020). "Indeed, CAFs help cancer cells to survive and grow in an environment with high or low levels of glucose, of glutamine and pH – showing yet another example of MYC influencing tumor microenvironment and making it more congenial for cancer cells." (PMID 33081056, 2020). "The PTCL-GATA3 subgroup, accounting for 33% of PTCL-NOS, has an enrichment of MYC and cytotoxic gene with poorer outcome while the PTCL-TBX21 subgroup that constitutes 49% of PTCL-NOS, has a tumor microenvironment gene signature and is associated with a favorable outcome." (PMID 33292562, 2020). "Similarly, MYC displays tumor-promoting (stimulation S-phase entry) and tumor-suppressing (DNA damage protection) mechanisms." (PMID 32076484, 2020). "We utilized MYC targets v1 and MYC targets v2 scores of gene set variation analysis and hypothesized that these scores correlate with tumor aggressiveness and survival outcomes." (PMID 33143224, 2020). "In this scenario, GSK-3 was acting as a tumor suppressor to inhibit c-MYC levels." (PMID 32365809, 2020). "Moreover, MYC is able to successfully support tumor progression by orchestrating active crosstalk between cancer cells and the host." (PMID 33081056, 2020). "Targeting of eIF4F in MYC-driven models of cancer greatly reduces tumor initiation." (PMID 32759815, 2020). "Adult Group 3 tumours lacked hallmark MYC amplifications, but had recurrent mutations in KBTBD4 and NOTCH1." (PMID 33172502, 2020). "One cluster was enriched with genes predicted to be involved in biological processes related to tumor progression (e.g., E2F targets, G2/M checkpoint, and MYC targets), whereas two clusters were enriched for immunological processes (e.g., allograft rejection, complement, and interferon-γ response)." (PMID 32024838, 2020).
tumor (continued). "Recent data shows that MYC is also over-expressed in circulating tumor cells (CTSs), suggesting that its target genes could be essential for the survival of cancer cells in the bloodstream." (PMID 33081056, 2020). "We cannot help but speculate that in the future the MYC score could be used as a prognostic biomarker to identify patients who will have increased tumor aggressiveness and worse prognosis." (PMID 33143224, 2020). "Additional evidence demonstrates that MYC is also involved in the recruitment of different elements of tumor microenvironment: from making tumor stroma more accommodating for tumor cells to helping evade immune responses to push a tumor to a more invasive and metastatic phenotype." (PMID 33081056, 2020). "MYC is expressed in TAMs as well, where it controls the expression of pro-tumor genes." (PMID 33081056, 2020). "MYC and Twist1 cooperate to remodel the tumor immune microenvironment." (PMID 31933479, 2020). "The over-expression of MYC may be one general mechanism by which tumor cells up-regulate the expression of immune checkpoint regulators, thereby evading immune surveillance." (PMID 33081056, 2020). "Thus, the uncontrolled activity of MYC observed in many types of cancers exacerbates ribosome biogenesis and promotes aberrant translation that sustains tumor progression." (PMID 33120992, 2020). "Similarly, the over-expression of MYC in metastatic tumor cells leads to the up-regulation of Id2 and, hence, to the repression of SEMA3F." (PMID 33081056, 2020). "Several mouse models have been generated to further examine the effects on tumor development following MYC expression in basal (which includes the stem cell compartment of the IFE, sebaceous gland and hair follicle) or suprabasal (terminally differentiating) keratinocytes." (PMID 32895364, 2020). "Additionally, EVs transport single-stranded DNA (ssDNA), which summarises genomic eccentricities such as oncogene amplifications (such as MYC) in the primary tumour." (PMID 33081785, 2020). "Combined inhibition of SMS and MYC signaling induces synergistic apoptosis and tumor regression." (PMID 32591507, 2020). "Treatment of cancer cells with KI-MS2-008 suppresses MYC-dependent tumor growth in vivo." (PMID 33628735, 2020). "At the transcriptomic level, tumours with high MYC mRNA and high ATR mRNA expression were also associated with higher tumour grade, high-risk Nottingham Prognostic Index (NPI), ER−, PR−, Genefu subtype (ER−/Her-2−), triple negative and PAM50.Basal phenotypes (all adjusted p values ≤ 0.01)." (PMID 30746633, 2019). "In addition, the role of c-MYC has been also related to chemoresistance and anti-apoptotic effect in different tumor types against different treatments, and c-MYC expression has been directly related to mesenchymal shift during carcinogenesis." (PMID 31027221, 2019). "Elevated MYC expression sensitizes tumor cells to apoptosis but the therapeutic potential of this mechanism remains unclear." (PMID 30728358, 2019). "These clients define new nodes that could be therapeutically targeted to disrupt the survival of tumor cells driven by MYC activation." (PMID 30902071, 2019). "The identification of these HSP70/BAG1 chaperone clients introduces new targets that could be therapeutically exploited to disrupt the survival of tumor cells driven by MYC activation." (PMID 30902071, 2019). "Interestingly, Genufu subtype (ER+/HER-2−/low proliferation), Her-2+, PAM50.Her-2 subtype and PAM50.Luminal A subtype were more common in tumours with low MYC mRNA and low ATR mRNA expressions (all adjusted p values ≤ 0.01)." (PMID 30746633, 2019). "We performed a chromatin immunoprecipitation (ChIP) assay in paired tumor and non-tumor liver tissues from HCC-B patients to investigate whether c-MYC plays a role in URI1 expression in HCC-B." (PMID 31739577, 2019). "Consequently, TNBC patients show elevated levels of MYC expression, which correlates with tumor progression with poor prognosis." (PMID 30076412, 2019).
tumor (continued). "Taken above, aberrant activation of CDK5 might be able to limit the tumor suppressing effect of BIN1 by blocking the BIN1/c-MYC interaction, consequently, overcoming the overexpression of CDK5 might further improve the prognosis of NSCLC patients." (PMID 31496920, 2019). "Among oncogenes, MYC has been found to have a pivotal role in the metabolic reprogramming of tumor cells by enhancing glucose uptake and glycolysis, lactate production and export, glutamine uptake and glutaminolysis, mitochondrial biogenesis, and oxidative phosphorylation." (PMID 31341534, 2019). "Integrins are stimulators of cancer cell proliferation and tumor angiogenesis linked to the Ras-ERK pathway by CAV-1, tyrosine kinase Fyn and Shc and integrin alpha-1 expression is directly regulated by oncogenic factor c-MYC." (PMID 31889941, 2019). "Furthermore, both isoforms of MDH and MTHFD were elevated in SCCs compared with NC lungs and were upregulated in MYC+N1ICD tumours." (PMID 31114017, 2019). "The results demonstrated that CDK5 knockdown could restore the tumor suppressing of BIN1 by inhibiting phosphorylation of c-MYC on Ser-62." (PMID 31496920, 2019). "As ATR inhibition is a promising anti-cancer approach, whether combining ATR inhibitor with endocrine therapy in MYC amplified tumours will be clinically relevant will be an interesting area for future investigation." (PMID 30746633, 2019). "Furthermore, we demonstrated that SPAG5 promoted tumor growth by increasing c-MYC transcriptional activity via interaction with MYCBP." (PMID 30736840, 2019). "On the one hand, c-MYC is a proto-oncogen involved in tumor development." (PMID 31027221, 2019). "In addition, identifying the unique vulnerabilities that arise in a MYC-driven tumour can reveal targetable synthetic lethal interactions." (PMID 31350286, 2019). "Thus, understanding the mechanisms of MYC-driven tumor progression/recurrence and integration of molecular-targeted therapies are critical to identifying novel and effective therapeutics for these high-risk patients." (PMID 31694585, 2019). "Although our previous studies demonstrated that GFI1 proteins cooperate with MYC to initiate MB formation, their role in tumor maintenance remains unclear." (PMID 30659187, 2019). "The implication of this observation is that modest MYC overexpression may, by virtue of evading intrinsic tumour suppression, exhibit enhanced tumour promoting activity compared with higher levels that overtly trigger apoptosis." (PMID 31032816, 2019). "Macroscopical inspection of liver, lung, spleen, and kidney organs did not indicate a presence of any abnormalities that might suggest tumor formation or malignant transformation processes induced by c-MYC-MSC." (PMID 30836996, 2019). "We further examined [U-13C]-glucose metabolism in MYC+N1ICD mouse tumours." (PMID 31114017, 2019). "Indeed, by SISH microscopy, we detected intratumoral genetic heterogeneity of c-MYC GCN in each tumor cell." (PMID 30733532, 2019). "Similarly, we reported that MYC inactivation in T-ALL triggers genome-wide changes in histone acetylation and methylation associated with cellular senescence and tumor regression." (PMID 31266538, 2019). "Interestingly, Genufu subtype (ER+/HER-2−/low proliferation) and PAM50.Luminal A subtype were common in tumours with low MYC mRNA and high ATM mRNA expressions all adjusted p values ≤ 0.01)." (PMID 30746633, 2019). "Although these data indicated Ctcf behaved as a tumor suppressor gene, which was also supported by somatic mutation burden of CTCF in a recent human pan-cancer study, contradictory results were seen in other models regarding the CTCF/MYC regulation axis." (PMID 31127282, 2019). "Therefore, the deregulation of MYC expression in this setting creates a MYC-dependent normal-to-tumour switch that can be measured in vivo." (PMID 31350286, 2019). "One of the anabolic pathways commonly activated in tumor cells is the MYC pathway." (PMID 30626133, 2019).
tumor (continued). "Moreover, it has been demonstrated that overexpression of c-MYC in immortalized mammary epithelial cells favored tumor formation via epigenetic cell reprogramming." (PMID 30283976, 2019). "Taken together, the MeDIP- and hMeDIP-seq analyses reveal genome-wide changes in 5mC and 5hmC distribution associated with a wide variety of biological processes upon MYC inactivation, indicating that MYC maintains tumor cell-specific DNA (hydroxy)methylation patterns in T-ALL." (PMID 31266538, 2019). "Furthermore, combination of JQ1 with EGFR inhibitor significantly reduced 97-H tumor growth in vivo, along with decreased level of p-MYC-Ser62." (PMID 30770740, 2019). "Taken above, these results revealed that presence of CDK5 could deactivate the tumor suppressing effect of BIN1 by mediating phosphorylation of c-MYC on Ser-62." (PMID 31496920, 2019). "Due to its oncogenic role, MYC is an attractive molecular target for tumor intervention therapy." (PMID 30760754, 2019). "However, the expression of glycolytic and serine biosynthesis enzymes in MYC-only tumours was similar to MYC+N1ICD tumours." (PMID 31114017, 2019). "In ER- tumours, MYC overexpressed tumours with high ATR protein levels had the worst survival." (PMID 30746633, 2019). "In summary, human SCCs specifically upregulated nine isoforms relative to NC and AdC tissues while MYC+N1ICD mouse tumours had the same isoform specificity in 8 out of 9 of these cases, which further supports an association between Notch activation and the SCC-distinguishing metabolism." (PMID 31114017, 2019). "We therefore hypothesize that tumor cells with concurrent MYC and BCL2 overexpression, such as DHL, may be effectively targeted through the combined treatment with XPO1 and BCL2 inhibitors." (PMID 31752970, 2019). "On the one hand, HUWE1 is able to enhance tumor cell proliferation by K63-poly ubiquitination and activation of the transcription regulator MYC, on the other hand, depletion or mutation of HUWE1 lead to increased MYC levels, thereby promoting skin and colon tumorigenesis." (PMID 31001145, 2019). "To preliminarily clarify whether presence of CDK5 could act as tumor promoter by effecting the interaction of BIN1/c-MYC, we detected both CDK5 and BIN1 expression status in NSCLC cells." (PMID 31496920, 2019). "To look at the impact of SNF5 on MYC in a more tumor-relevant setting, we asked whether SNF5 modulates the interaction of MYC with chromatin in the context of MRT, which is driven by SNF5 loss, and where MYC target gene signatures are repeatedly activated." (PMID 31043611, 2019). "Here, we demonstrate that XPO1 inhibition in DHL tumor cells abrogates MYC protein expression." (PMID 31752970, 2019). "Therefore, one possibility is that tumors exploit MYC-dependent sequestration of SPT5 to repress tumor-suppressive genes, providing an explanation for the selection of high levels of MYC during tumor progression." (PMID 30928206, 2019). "Indeed, etomoxir treatment inhibits mammosphere formation and tumor growth in vivo in TNBC tumors bearing high MYC expression." (PMID 30967773, 2019). "Furthermore, immunohistochemical staining suggested that the expression of TRIP13, Ki67 and c-MYC was significantly reduced in TRIP13-knockdown tumours compared with controls, while the expression of FBXW7 was increased." (PMID 31740732, 2019). "Moreover, suppression of XPO1 with selective inhibitors of nuclear export (SINEs) has been shown to downregulate MYC expression in several tumor types." (PMID 31752970, 2019). "Moreover, tumour growth is dependent upon sustained deregulated MYC expression, further demonstrating addiction to this potent oncogene and regulator of gene transcription." (PMID 31350286, 2019). "This further confirms SAE2 as an attractive drug target to inhibit MYC-driven tumours." (PMID 31455158, 2019). "Interestingly, treatment with MYC-siRNA has been found to result in significant reduction in vivo tumor growth." (PMID 30626133, 2019).